MTOR (mechanistic target of rapamycin kinase)
Diseases named in the same sentence as MTOR in open-access papers (continued):
Sharing a sentence is not in itself a finding about the gene and the disease.
melanoma (continued). "Our study provides a molecular mechanism by which BRAF-mutant melanoma cells gain resistance to BRAFi and MEKi combination therapy, and implicates mTOR inhibition for further treatment of CR patients." (PMID 34304249, 2021). "In some cancer entities such as melanoma, PD-1 activation in cancer cells led to mTOR activation, in turn leading to cancer progression; so far, it has not been described for cancer cells in HNSCC." (PMID 34778030, 2021). "As previously stated, PI3K/AKT/mTOR signalling appears to be greatly involved in melanoma pathogenesis in both human and canine species." (PMID 34895222, 2021). "Our last studies have also demonstrated the efficacy of mTOR everolimus inhibitor in combination with MEK kinase inhibitor—AS-703026 or AKT kinase inhibitor—MK-2206 in the induction of apoptosis in melanoma cells." (PMID 31586300, 2020). "We found that Ole potentiates the cytotoxic effect of everolimus against BRAF melanoma cells inhibiting pAKT/mTOR pathway, as measured by the decrease of pAKT/S6." (PMID 32013090, 2020). "Treatment of melanoma cells: Lu1205 and WM793 with 5 nM concentration of everolimus resulted in a significant decrease in the level of phosphorylated mTOR (Ser2448) kinase associated with the activity of the mTORC1 complex." (PMID 31586300, 2020). "We identified pyridinyl imidazole compounds SB2020190, SB203580, and SB590885 as dual inhibitors of mutant BRAF kinase and mTOR signaling in melanoma cells." (PMID 32531927, 2020). "It is reported that high expression of HSP90 and PI3K/AKT/mTOR pathway components in melanoma tumors and this expression correlates with poor survival in melanoma patients." (PMID 33490091, 2020). "It seems, therefore, important to undertake research on the use of a combination of protein kinase inhibitors with particular emphasis on mTOR inhibitor everolimus in reducing the invasiveness of melanoma cells." (PMID 31586300, 2020). "It has been suggested that melanoma formation requires cross-talk of the PI3K/Akt/mTOR and Ras-ERK pathways." (PMID 32793477, 2020). "The authors suggested that other mechanisms in the biology of melanoma allow mTOR pathway to be bypassed, and one of the suggested mechanisms involves molecules controlling apoptosis." (PMID 33071785, 2020). "We found that both human and mouse melanoma cells have high phosphorylated mTOR and p70S6K cell populations, indicating elevated mTORC1 activity in melanoma tumor cells." (PMID 32984331, 2020). "Taken together, these data indicate that the mTOR signaling pathway is active in melanoma cells and can affect import of TFEB into the nucleus." (PMID 32881934, 2020). "In this regard, it has been demonstrated that PG is able to recognize and inhibit the Akt/mTOR pathway in melanoma cells." (PMID 32899258, 2020). "Our results suggest that alteronol induces cyto-protective autophagy in melanoma cells through inhibition of Akt/mTOR pathway, thus attenuates apoptosis and promotes melanoma cell EMT through TGF-β/Smad3 pathway." (PMID 32265437, 2020). "To evaluate the molecular signaling events involved in the mTOR pathway, we analyzed the upstream events that regulate the mTOR pathway in melanoma cells exposed to CAP, SN, and CAP and SN co-treatment conditions." (PMID 32178401, 2020). "Our data show that the PI3K/Akt/mTOR and HIF-1 cross-talk pathways are implicated in mouse melanoma development and that CDPs targeted these pathways." (PMID 32793477, 2020). "Treatment of melanoma cells with everolimus led to a significant decrease in the level of both phosphorylated: mTOR (Ser2448) and mTOR (Ser2481) as well as their downstream effectors." (PMID 31586300, 2020). "In conclusion, we demonstrated that the dual inhibition of mTOR and DNA-PK by CC-115 led to cytotoxic effects of varying degrees in most of the melanoma cell lines." (PMID 33297429, 2020).
melanoma (continued). "We then confirmed the functional importance of mTOR-HIFα signaling pathway in glucose metabolism suppression and senescence induction in melanoma cells mediated by baicalein and baicalin." (PMID 32984331, 2020). "Our studies also confirm that low nanomolar concentrations of the everolimus mTOR inhibitor in combination with the MEK kinase inhibitor AS-703026 or AKT kinase inhibitor-MK-2206 induce apoptosis in melanoma cells." (PMID 31586300, 2020). "All in all, Polyphyllin I induces melanoma cell autophagy and apoptosis, arrest melanoma cells stage at G0/G1 by inhibiting PI3K/Akt/mTOR signal pathway, thus suppressing melanoma progression." (PMID 32733943, 2020). "Next, we analyzed the potential impact of these dynamic changes of mTOR subcellular localization on mTORC1 activity in melanoma cells." (PMID 32531927, 2020). "The combination between pimasertib, a MEK1/2 inhibitor, and voxtalisib, a dual PI3K/mTOR inhibitor among patients affected by solid tumors, including melanoma, was tested in a phase Ib trial in 146 patients." (PMID 32850962, 2020). "Our previous work regarding adipocytes and melanoma revealed the fact that adipocyte-conditioned medium induced proliferation and migration of B16BL6 melanoma cells via Akt/mTOR signaling." (PMID 32722030, 2020). "When the BRAF and PI3K/AKT/mTOR signaling pathways are simultaneously inhibited, the growth of drug-resistant BRAF mutated human melanoma cells can be inhibited." (PMID 32175074, 2020). "It has also been demonstrated that MDSCs directly enhanced B16 melanoma cell proliferation by mTOR signaling." (PMID 32092078, 2020). "We have presented evidence for the inactivation of TFEB and ZKSCAN3 by the co-effect of CAP and SN and blockage of the mTOR/EGFR pathway that provides a compelling model to explain the suppression of melanoma and resultant autophagy-lysosome activation." (PMID 32178401, 2020). "Despite great interest in mTOR inhibitors in cancer treatment, a clinical study conducted in patients with metastatic unresectable malignant melanoma treated with everolimus (mTOR inhibitor) has shown limited effects." (PMID 33071785, 2020). "A mutation in BRAF (BRAF V600E) affects various signaling pathways, including mitogen activated protein kinase (MAPK) and PI3K/AKT/mammalian target of rapamycin (mTOR) in melanoma." (PMID 32626712, 2020). "Mechanistically, we identify that the suppression of baicalein and baicalin on melanoma cells is due to inhibition of tumor cell glucose uptake and metabolism by affecting the mTOR-HIF-1α signaling pathway." (PMID 32984331, 2020). "In our previous study we found that Ole affects both the proliferation and the viability of A375 BRAF melanoma cells and potentiates their therapy response through pAKT/mTOR pathway." (PMID 32013090, 2020). "We performed a functional rescue experiment with over-expression of the mTOR upstream activator Rheb gene in melanoma cells (retrovirus-based Rheb)." (PMID 32984331, 2020). "Here, we have used a syngeneic, experimental spine metastases model in the mouse to test the efficacy of mTOR inhibition and anti-angiogenesis on the formation and progression of spinal melanoma metastases." (PMID 32140451, 2020). "Approximately 40–60% of melanoma is due to a mutation in the BRAF gene that promotes MEK-MAPK and PI3K-AKT/mTOR pathway activation and melanoma proliferation." (PMID 32178401, 2020). "Tumor cell-intrinsic PD-L1 promotes melanoma tumorigenesis in vivo through activating the mTOR signaling." (PMID 33363153, 2020). "miR-410-3p-targets axis was found to be associated with cancer signaling and BRAFi resistance pathways, including MAPK, mTOR, and neurotrophins microRNAs contribute to the development and progression of melanoma." (PMID 32555626, 2020). "Proximity to mechano-regulating fibroblasts can induce pathway changes to PIK3CA/mechanistic target of rapamycin kinase (MTOR) and switch the phenotype of melanoma cells to the mesenchymal state." (PMID 32410672, 2020).
melanoma (continued). "Co-immunoprecipitation experiments supported an interaction between oncogenic Ras and endogenous mTOR in N-Ras mutant melanoma cells." (PMID 31497244, 2019). "The flavonoid fisetin impeded EMT in A375 melanoma cells by hindering the PI3K/Akt/mammalian target of rapamycin (mTOR) pathway." (PMID 30708951, 2019). "Jiang and Liu reported that miR-25 target the RNA-binding motif protein 47 (RBM47) and activated the PI3K/Akt/mTOR signaling pathway in melanoma cells." (PMID 31370278, 2019). "The mTOR signaling, which is one of the well known pathways in melanoma, controls cell growth, proliferation, and survival." (PMID 31594284, 2019). "Melanoma cell-intrinsic PD-1 cooperates with PD-L1 to promote tumorigenesis and modulates downstream effectors of mTOR signaling." (PMID 30925913, 2019). "Recent studies have shown that inhibition of PI3K/AKT/mTOR signaling sensitizes melanoma cells to TMZ." (PMID 30866426, 2019). "Collectively, our results indicated that Ku80 inhibited apoptosis of melanoma cells, and promoted their proliferation through mTOR/Akt signaling pathways." (PMID 31023624, 2019). "Subsequent experiments demonstrated that the mTORC2 components, Rictor and MAPKAP1, preferentially co-immunoprecipitated with oncogenic compared to wild-type Ras and were required for mutant Ras and mTOR proximity in mutant N-Ras melanoma cells." (PMID 31497244, 2019). "Then, we confirmed that the mTOR/VEGFA pathway was activated during the process of kindlin-2-induced melanoma progression and angiogenesis." (PMID 31427543, 2019). "There is a study about skin cancer that identified that PYCR2 was abundantly present in melanoma cells and regulated the Akt/mTOR pathway." (PMID 31428683, 2019). "MMP9 expression is regulated by several pathways and epigenetic alterations; overexpression can be the result of aberrant activation of the MAPK and AKT/mTOR signaling pathways almost always found in melanoma." (PMID 31623313, 2019). "Treatment with melittin caused a reduction in the phosphorylation of PI3K, AKT and mTOR as well as MAPKs including ERK and p38 in melanoma cells." (PMID 30866426, 2019). "In a melanoma patient in whom programmed-death 1 (PD-1) blockade resulted in organ rejection and colitis, the addition of the mTOR inhibitor sirolimus resulted in ongoing anti-tumor efficacy while promoting allograft tolerance." (PMID 31624262, 2019). "This evidence underscores the importance of targeting low pH of melanoma, likely combining mTOR/NF-kB inhibitors." (PMID 31275384, 2019). "Mitogen‐activated protein kinase and PI3K/AKT/mTOR pathways represent the key signaling cascades involved in melanoma development and progression." (PMID 31115969, 2019). "Taken together, these results suggest that BV and melittin inhibit the growth and metastatic potential of melanoma cells by downregulating both PI3K/AKT/mTOR and MAPK signaling pathways." (PMID 30866426, 2019). "MMP9 expression is regulated by several pathways and epigenetic alterations; overexpression is due to the aberrant activation of the MAPK and AKT/mTOR signaling pathways almost always found in melanoma." (PMID 31623313, 2019). "In a recent study, xCT was reported to be modulated by mTOR signaling in human melanoma subjected to radiation." (PMID 31929797, 2019). "Taken together, these data indicate that upregulation of TRIM44 activates the AKT/mTOR pathway, which in turn promotes melanoma cell EMT." (PMID 30922374, 2019). "Rapamycin, its analogs and other protein kinase inhibitors have been investigated for targeting the main mTOR hub in melanoma cells." (PMID 31370278, 2019). "mTOR inhibiting agents, including RAD001, are effective in inhibiting the PI3K/AKT/mTOR pathway, although several reports indicate that mTOR inhibitors have limited single-agent activity against melanoma." (PMID 30544808, 2018). "Re-expression of Phd2 in Phd2−/− melanoma cells suppresses the Akt–mTOR pathway, further supporting the involvement of this pathway." (PMID 30575721, 2018).
melanoma (continued). "Particularly promising are the results with regard to the decrease in melanoma cells invasiveness after N-cadherin gene silencing and the use of everolimus inhibitor of the mTOR pathway." (PMID 29492694, 2018). "The object of this study is recognition of the possible role of N-cadherin and selected downstream protein kinases: PI3K, ERK1/2, and mTOR in cell invasion in malignant melanoma." (PMID 29492694, 2018). "Collectively, these data suggest that SMI-4a induces autophagy by inhibiting AKT/mTOR signaling, and consequently retards melanoma cells growth." (PMID 29483938, 2018). "On the other hand, 250 μM Ole reduced the cell proliferation rate of treated melanoma cells and inhibited pAKT/mTOR pathway, assessed by the decrease of densitometric analysis of AKT/S6 phosphorylation." (PMID 30544808, 2018). "Here the authors show that PHD2 is downregulated in melanoma and that PHD2 depletion, in a mouse model, promotes the progression of benign melanocytic lesions into melanoma, via activation of the Akt/mTOR signaling cascade." (PMID 30575721, 2018). "PI3K/AKT/mTOR pathway inhibitors have been evaluated in dogs, inhibiting growth of canine melanoma cells in vitro and in a canine melanoma xenograft model." (PMID 29385676, 2018). "Studies suggested that many melanomas have low AMPK and high mTOR activity due to mutations that enable them to escape energetic stress and continue proliferation." (PMID 30651927, 2018). "Separate use of inhibitors: U0126 (ERK1/2) or everolimus (mTOR) reduced melanoma cell invasion by approximately 21–25% (p < 0.005), whereas treatment with LY294002 (PI3K) reduced it by only about 15% (p < 0.005)." (PMID 29492694, 2018). "Cross-resistance to BRAF-, MEK1/2- and PI3K/mTOR-specific inhibitors in BRAF mutant melanoma cells has been demonstrated." (PMID 29296217, 2017). "The greatest simultaneous decline of cyclin D1, CDK4 kinase, and cyclin D3 and CDK6 kinase was observed after treatment of melanoma cell with the combination of inhibitors: mTOR—everolimus, with ERK1/2 inhibitor—U126 or B-RAF-GDC-0879." (PMID 29214525, 2017). "To further explain the cell cycle arrest, we also investigate the effect of itraconazole on the mTOR pathway in these melanoma cells by Western blot assay." (PMID 28212537, 2017). "We report the first case of a collision tumor composed of adenocarcinoma and melanoma with a TSC1 mutation that objectively and durably responded to mTOR inhibition." (PMID 28302097, 2017). "In the case of treatment of melanoma cells with each of inhibitors used in individual mode, the best results were obtained for mTOR inhibitor (either everolimus or rapamycin)." (PMID 29214525, 2017). "In this study, we evaluated the synergistic anti-tumour efficacy of the mTOR inhibitor everolimus in conjunction with nsPEFs against melanoma." (PMID 28054548, 2017). "Treatment of A375 and Hs294t melanoma cells with cryptolepine greatly reduced the total protein levels of mTOR and its phosphorylation in a concentration-dependent manner." (PMID 28473727, 2017). "The PI3K/mTOR/AKT pathway is activated in most melanomas, but mTOR inhibitors used singly have limited activity against advanced melanomas." (PMID 28054548, 2017). "Such a ROS-induced repression of mTOR triggering autophagy was described in a melanoma cell line, whereby ATM activates AMPK via the AMPK kinase and ATM effector LKB1 (also known as STK11)." (PMID 28213588, 2017). "We noticed significant basal phosphorylation of the ERK1/2 and AKT/mTOR components in all four melanoma cell lines which can be explained because of a constitutively active RAS, harboring the V600E mutation in these cell lines." (PMID 28223541, 2017). "With human malignant melanoma cells, 40 μM apigenin significantly inhibited cell migration and invasion though the AKT/mTOR pathway in melanoma A375 and C8161 cell lines." (PMID 29034071, 2017).
melanoma (continued). "Rictor, the key component of the rapamycin‐insensitive complex of mTOR (mTORC2), is up‐regulated in several cancers, especially in melanomas with poor prognosis." (PMID 28699701, 2017). "The aim of this study was the recognition of the possible role of selected protein kinases: PI3K, ERK1/2, and mTOR in cell proliferation and cell cycle in malignant melanoma." (PMID 29214525, 2017). "Our findings indicate that nsPEFs in combination with an mTOR inhibitor can be used as a potential treatment approach for advanced melanoma." (PMID 28054548, 2017). "These pathways including ERK1/2, STAT1, STAT3, STAT5, AKT and mTOR are known to drive the tumoral progression in melanoma cells and are found to be crucial in the interactions of melanoma with its microenvironment and progression to metastasis." (PMID 28223541, 2017). "In summary, our results demonstrated that LKB1 inactivation plays a cooperative role with BRAF mutation in promoting melanoma cells invasion and migration by activation of PI3K/Akt/mTOR signaling pathway and MMP-2 expression." (PMID 29371951, 2017). "On the other hand, PP1 shRNA knockdown or exogenous expression of constitutively activate Akt1 (CA-Akt1) restored Akt-mTOR activation and significantly attenuated liposomal C6-mediated cytotoxicity and apoptosis in melanoma cells." (PMID 27631768, 2016). "Unlike T cells in which PD-1 ligation causes inhibition of PI3K/Akt and MAPK pathways, PD-1 ligation in melanoma cells was found to activate these pathways and to induce mTOR signaling." (PMID 27510264, 2016). "Many studies explore the potential use of dual inhibition of MAPK and PI3K/AKT/mTOR which results in growth inhibition in NRAS mutant melanoma and neuroblastoma." (PMID 26821351, 2016). "Taken together, the in-vitro and in-vivo experiments indicated that co-targeting of MEK1/2 and PI3K/mTOR has improved anti-tumor activity compared to co-targeting of mutant BRAF and PI3K/mTOR even in melanoma cells with an intrinsic cross-resistant phenotype." (PMID 26678033, 2016). "We have now identified a novel mechanism of action of A-SMase in melanomas and found that the enzyme down-regulates the autophagic process via activation of the mTOR pathway." (PMID 27107419, 2016). "This supports the importance of tumor-stroma proximity for sustaining mTOR activity in BRAFi-treated melanoma." (PMID 26918352, 2016). "Molecularly, liposomal C6 activated protein phosphatase 1 (PP1) to inactivate Akt-mammalian target of rapamycin (mTOR) signaling in melanoma cells." (PMID 27631768, 2016). "It is now well established that the FAK/PI3K/Akt/mTOR pathway plays a critical role in the development of melanoma." (PMID 26621838, 2016). "The PI3K/Akt/mTOR signaling axis is central to the carcinogenesis in many human cancers including melanoma, AML, prostate, colon, breast and non-small lung cancer." (PMID 26536665, 2016). "Recently, we showed that fisetin inhibited the expression of PI3K and phosphorylation of AKT and mTOR in melanoma cell lines and xenograft tumors." (PMID 26517521, 2016). "After activation of FAK via integrins, the PI3K/Akt/mTOR pathway is involved in the proliferation, migration, and angiogenesis of many cancers, including melanoma." (PMID 26621838, 2016). "Since, Akt-mTOR activation plays a vital role in melanoma cell survival and proliferation, our results suggest that liposomal C6 activates protein phosphatase to inhibit Akt-mTOR signaling and melanoma cell proliferation." (PMID 27631768, 2016). "Eradication of pS6high melanoma cells by co-targeting mTOR, potentiated an anti-cancer effect in the BRAFi-treated melanoma models with abundant stromal contacts." (PMID 26918352, 2016). "We also combined C012 with the PI3K inhibitor, PI-103, and rapamycin, targeting the mTOR signal, which has been shown to have pre-clinical significance in preventing melanoma tumor growth." (PMID 27447557, 2016).